GPC1 (glypican 1)
Diseases named in the same sentence as GPC1 in open-access papers (continued):
Sharing a sentence is not in itself a finding about the gene and the disease.
tumor (continued). "So glypican-1 and glypican-6 serve largely as tumour promoters, and glypican-3, and glypican-4 inhibit BC." (PMID 41463344, 2025). "The difference between glypican-1 expression of the two tumor types was highly significant (p value < 0.001)." (PMID 39797955, 2025). "The effective production of GPC1 in tumor cells, along with continuous antigen delivery and immune activation, underscores the promise of this approach for PDAC and other cancers." (PMID 40282924, 2025). "Since inhibiting GPC1 activity using an anti-GPC1 monoclonal antibody has shown potential anti-tumor effects in a GPC1-positive ESCC xenograft model, it is expected that GPC1 targeted therapies can be developed for other GPC1-positive solid tumors." (PMID 39797955, 2025). "On the other hand, the relationship between GPC1 positive immunoreactivity and tumor grade was highly significant (p < 0.001), where all eight grade two cases included in the study were GPC1 negative." (PMID 39797955, 2025). "This adds the GPC1 marker to the list of markers that can help in revealing the exact tumor cell lineage of NSCLC, especially in poorly differentiated cases not identified by the conventional stain and need further IHC studies." (PMID 39797955, 2025). "Researchers can utilize the GPC1-expressing PANC02 cells as a model to accurately observe and study how cytotoxic T cells identify and respond to the GPC1 antigen displayed by tumor cells." (PMID 40282924, 2025). "A previous study revealed a significant relation between GPC1 expression and some histopathological data like tumor size, grade, stage, and lymph node metastasis." (PMID 39797955, 2025). "Compared with controls, the expression of GPC1+ exosomes were markedly higher in the tumor tissues and plasma of patients with CRC prior to surgical treatment." (PMID 40612948, 2025). "GPC1, a crucial heparan sulfate proteoglycan involved in key signaling pathways that promote tumor growth and spread, has generated significant attention." (PMID 40282924, 2025). "TAAs, such as Glypican-1 (GPC1) and the melanocyte differentiation antigen glycoprotein (gp100), are attractive targets due to their increased expression in tumor cells compared to normal cells." (PMID 40282924, 2025). "Proteomics measures proteins, such as glypican-1 (GPC1), to gain insights into tumor function and potential diagnostic markers." (PMID 40227568, 2025). "The 3D spheroid invasion assay was conducted to evaluate the effect of anti-GPC1 mAb on the invasion potential of A549 and H460 tumor cells that were either monocultured or cocultured with LL97A fibroblasts." (PMID 38966167, 2024). "Given that the anchorage-independency bestows upon tumor cells the potential to colonize distant organs and form malignant lesions, anti-GPC1 mAb treatment is likely to be effective against tumorigenesis and cancer metastasis." (PMID 38966167, 2024). "Tumor nodules were found in the lungs of two more animals in the 10 mg/kg anti-GPC1 mAb group during the macroscopic inspection." (PMID 38966167, 2024). "The expression level of GPC-1 in 12 or 10 tumor tissues was significantly higher or lower than that in their normal neighboring tissues (P < 0.05)." (PMID 38982153, 2024). "Tumor-bearing mice treated with 50 mg/kg anti-GPC1 mAb had 43-, 17- and 2-fold increase in the mean anti-GPC1 mAb plasma levels as compared with the control, 1 mg/kg and 10 mg/kg anti-GPC1 mAb groups, respectively (P < 0.01 for all)." (PMID 38966167, 2024). "Selective expression of MSLN, MUC4, ANXA10, and GPC-1 in the neoplastic tissue compared to non-tumor ductal and acinar tissues (p < 0.001)." (PMID 39062863, 2024). "They found that when they tested the anti-tumor effects of human CAR T cells against GPC1 in xenograft solid tumor models, the rate of tumor eradication was slower than in immunocompetent models using murine GPC1-targeting CAR T cells." (PMID 39335157, 2024).
tumor (continued). "The inhibitory effect of anti-GPC1 mAb on tumor growth was evaluated in an orthotopic lung tumor model." (PMID 38966167, 2024). "The expression of GPC-1 was significantly affected body weight (P = 0.0029), race (P = 0.016), tumor grade (P = 0.021), and gender (P = 1e−04) on HCC patient overall survivals." (PMID 38982153, 2024). "The following clinical factors were significantly correlated with the preoperative high GPC1 concentration: male, tumor size ≥30 mm, venous invasion, pT factor ≥2, pStage ≥3, residual tumor, and distant metastatic recurrence." (PMID 39300946, 2024). "In the second in vivo study, the anti-GPC1 mAb treatment was started two weeks after the orthotopic inoculation of A549 tumor cells for early blockage of GPC1 activity." (PMID 38966167, 2024). "Further experiments on the nude mice with orthotopic MDA-MB-231 tumors revealed that GPC1+ circulating exosomes (crExos) are derived from cancer cells in tumor-bearing mice." (PMID 38962276, 2024). "The levels of miR-96-5p and miR-149 in patients influence the expression of GPC1 protein and the secretion of GPC1-positive exosomes from tumor tissues." (PMID 38298209, 2024). "Since inhibition of GPC1 activity with an anti-GPC1 mAb has shown promising anti-tumor effect in a GPC1-positive ESCC xenograft model, it is anticipated that GPC1 targeted therapies can be developed for other GPC1-positive solid tumors." (PMID 38966167, 2024). "When anti-GPC1 mAb was administered to tumor-bearing mice, the inhibitory effect of anti-GPC1 mAb on the orthotopic lung tumor growth was not statistically significant." (PMID 38966167, 2024). "Despite this, they concluded that the level of GPC1+crExo in plasma enabled them to determine tumor size and distinguish between patients who underwent tumor resection and those who did not." (PMID 39698536, 2024). "In this study, the anti-tumor effect of an anti-GPC1 mAb was evaluated in A549 and H460 NSCLC cell lines and LL97A human lung fibroblasts using a variety of 2D and 3D monoculture and co-culture models and in an orthotopic A549 lung tumor xenograft model." (PMID 38966167, 2024). "The percentage of GPC1-positive exosomes in tumor tissues and plasma is significantly higher in CRC patients, approximately fourfold and over 10-fold, respectively." (PMID 38298209, 2024). "The difference in molecular response to anti-GPC1 mAb treatment between monocultured and co-cultured lung fibroblasts and tumor cells implicates that anti-GPC1 mAb impairs the reciprocal crosstalk between tumor cells and tumor-associated fibroblasts." (PMID 38966167, 2024). "In this regard, the tumor cell/fibroblast coculture spheroids were used to evaluate the anti-invasion potential of anti-GPC1 mAb." (PMID 38966167, 2024). "Overall, it has been demonstrated that reduction of GPC1 activity through molecular or pharmacological interventions results in suppression of growth factor induced tumor cell growth, suggesting the potential of GPC1 as a druggable therapeutic target." (PMID 38966167, 2024). "Overall, these results suggest that anti-GPC1 mAb treatment inhibits fibroblast-led collective tumor cell invasion." (PMID 38966167, 2024). "The ability of AT101, in a single injection, to target the GPC1 protein on the cell surface and activate the immune response at the tumor prompted us to investigate its efficacy as an antibody-based immunotherapeutic in the PDAC xenograft mouse model." (PMID 38017492, 2023). "A high accumulation of [89Zr]GPC1 mAb was observed in the tumor xenograft 1 d after administration (SUVmax, 3.85 ± 0.10), and this level then gradually decreased until day 7 (SUVmax, 2.16 ± 0.30)." (PMID 37827841, 2023). "On the contrary, expression of GPC-1 in tumor tissue was significantly higher in the stroma and glandular epithelium (16/20, 80%) compared to normal paratumor tissue (2/20%)." (PMID 37649964, 2023).
tumor (continued). "In recent years, liquid biopsies to isolate circulating tumor DNA (ctDNA), circulating tumor cells (CTCs), circulating exosomal miRNA, and exosomal GPC1 for the early detection of PC have re ceived much attention." (PMID 36899319, 2023). "Glypican-1 (GPC1) is overexpressed in several solid cancers and is associated with tumor progression, whereas its expression is low in normal tissues." (PMID 37827841, 2023). "Elevated ectopic GPC1 expression corresponded to large tumor diameters and poor overall survival, indicating that it is a prospective prognostic marker for PDAC." (PMID 36980662, 2023). "The selected targets were patient-specific, as the analysis of another individual’s HPV+ OPSCC, showed that although some interactions, such as VEGFA/NRP1 and VEGFA/GPC1 were present, the most active L-Rs in the tumor were VEGFA/NRP2 and EGFR-related pathways." (PMID 37704757, 2023). "A CAR with specificity for both human and mouse glypican 1 has been described and elicited anti-tumour activity both in vitro and in vivo." (PMID 36831514, 2023). "The BXPC3 cells of the explanted tumor masses retained GPC1 expression as determined with the commercial anti-GPC1 polyclonal antibody." (PMID 38017492, 2023). "Among the multiple tumor antigens targeted for immunogenic therapeutic applications is Glypican-1 (GPC-1), an overexpressed member of heparan sulfate proteoglycan in PCa." (PMID 37738978, 2023). "In a comparison between a BxPC-3 and a BxPC-3 GPC1-knockout tumor, mild accumulation was observed 24 h after the administration of [89Zr]GPC1 mAb." (PMID 37827841, 2023). "The cross-reactivity of D4 to both human and murine GPC1 offers a tool to evaluate on-target off-tumor toxicities." (PMID 37031249, 2023). "The results showed that the use of shRNA to suppress GPC-1 had a significant impact on restraining tumor growth, a result that was further augmented in the presence of Pictilisib." (PMID 37649964, 2023). "In their study, it was found that this GPC-1 targeting ADC showed significant anti-tumor activity in both in vivo and in vitro models." (PMID 38203714, 2023). "The results produced consistent findings of increased GPC-1 mRNA in tumor tissues compared to normal paratumor tissue." (PMID 37649964, 2023). "PERTINENT FINDINGS: [89Zr]GPC1 mAb PET showed high tumoral uptake in the early phase after administration, whereas targeted α-therapy using [211At]GPC1 mAb successfully suppressed tumor growth." (PMID 37827841, 2023). "[211At]GPC1 mAb with internalization ability exhibited tumor growth suppression, highlighting the potential of a theranostic approach targeting GPC1." (PMID 37827841, 2023). "We selected ESO-26 cells for in vivo tumor experiments in BALb/c nude mice since this cell line expressed higher GPC-1 levels and showed greater resistance to Pictilisib compared to OE-33 cells." (PMID 37649964, 2023). "Tumor growth suppression was observed in PANC-1 xenograft mice after the administration of [211At]GPC1 mAb clone 01a033 (antibodies with internalization ability) compared with nonradiolabeled GPC1 mAb clone 01a033." (PMID 37827841, 2023). "Tumor marker glypican 1 was detected in all samples of pancreatic adenorcarcinomas and absent from benign samples." (PMID 35991837, 2022). "Our studies reveal a novel and unexpected functional specialization of an HSPG with major implications for the prominent role of GPC1 in tumor progression." (PMID 35348113, 2022). "Enzyme-linked immunoassay (ELISA) is used for more specific capturing of tumor-derived exosomes by applying specific antibodies against tumor markers such as Glypican-1 (GPC-1), Caveolin-1 (CAV1), or heat shock protein 90 (HSP90)." (PMID 35033106, 2022). "Immunohistochemistry showed a weak GPC1 signal in cells within the tumor, but a strong GPC1 signal was observed in fibroblasts surrounding the cancer cells." (PMID 36142190, 2022).
tumor (continued). "Both GPC1 and GOT1 genes were upregulated in tumor tissues, and were implicated in poor ESCA prognosis (p < 0.05)." (PMID 35794622, 2022). "The percentage of GPC1+ EVs and the GPC1 protein expression in EVs from tumour tissues and plasma of CRC patients before surgical treatment was significantly elevated compared to that in the peritumoural tissues and the plasma of healthy controls." (PMID 36407096, 2022). "Equally important, a combination of HER2-targeted CAR-T cells with a blockade of PD-1 or GPC1 significantly enhanced tumor-killing activity in a mouse model, while anti-PD1 antibody or CAR-T cells alone showed partial inhibition of tumor growth." (PMID 35326556, 2022). "Both the ANXA2 and GPC1 mRNA levels were significantly overexpressed in the tumor tissues compared with the corresponding peritumoral tissues (P < 0.001)." (PMID 33712571, 2021). "Glypican-1 is a cell surface proteoglycan that presents in a variety of solid tumors and modulates tumor growth, invasion and progression." (PMID 33903283, 2021). "This strengthens our findings on the prognostic value of GPC1, since GPC1 is not only present in the tumor microenvironment, but can be found in tumor cells themselves." (PMID 33742285, 2021). "Among the identified genes, ALDOB was associated with a low risk, while five genes (GPC1, ALDOC, ENO2, SERPINE1, and SLC2A3) were associated with a high risk of developing tumor malignancy." (PMID 33737938, 2021). "ANXA2 and GPC1 proteins were both primarily located on the cell membrane and in the cytoplasm of tumor cells." (PMID 33712571, 2021). "Treatment of xenografted mice with GPC1-GEM-NPs showed a higher tumor inhibitory effect than in controls." (PMID 34249755, 2021). "A third example with gold nanoparticles, that exploits the pancreas tumor targeting activity of GPC1, uses gold nanosystems for near-infrared fluorescence (NIRF)/MRI, loaded with gemcitabine: GPC1-GEM-NPs." (PMID 34249755, 2021). "The concentration of these GPC1 positive vesicles was more than 10 times higher than that in the plasma of healthy subjects, and the level of GPC1 protein was significantly increased in tumor tissues." (PMID 34094979, 2021). "Targeting glypican-1 using anti-glypican-1 monoclonal antibody restrained tumor growth and promoted apoptosis in ESCC PDX models." (PMID 33903283, 2021). "Circulating GPC1-expressing exosomes, several circulating RNAs, and circulating tumor DNA have all been proposed as potential prognostics; however, none have been clinically implemented." (PMID 34733417, 2021). "Exosomes from patients (PDAC, n=190) showed higher expression of GPC1 than did those from healthy donors (n=100), and the higher expression was correlated with higher tumor burden and lower survival." (PMID 34249755, 2021). "Based on these results, ITGA2, ITGAV, and GPC1 were used to isolate tumor-derived EVs in subsequent experiments." (PMID 34948417, 2021). "We demonstrated that CAR-T cells enhanced the CTL induction and generated immunological memory against non-GPC1 endogenous tumor antigens." (PMID 32228854, 2020). "Glypican-1 (GPC1) which is abundant in the contents of tumor-derived exosomes, showed higher specificity than serum CA-199 or free GPC1 (100% vs. 79.49% vs. 82.14%) to discriminate pancreatic tumor tissue from normal tissue." (PMID 32746854, 2020). "GPC1-specific human hCAR-T cells specifically recognized hGPC1-positive tumor cells and inhibited tumor growth in xenograft mouse model." (PMID 32228854, 2020). "Compared with PBS and control ADC, GPC-1-ADC administration significantly inhibited BxPC-3 xenograft growth as assessed by tumour volume and weight." (PMID 32152502, 2020). "Further, the treatment of these stromal cells with tumor-conditioned media from PC-3 cells transfected with GPC-1 shRNA increased the expression of extracellular matrix components, endocrine and paracrine biomolecules, and migration markers." (PMID 33330442, 2020).
tumor (continued). "Glypican-1 (GPC1) is a cell-surface heparansulphate proteoglycan expressed in normal fetal tissues and tumor cells." (PMID 32228854, 2020). "Playing a critical role in tumour cell growth, invasion and metastasis as a growth factor co-receptor, GPC-1 is overexpressed in a variety of solid tumours, including PCa." (PMID 33302918, 2020). "Understanding the mechanistic connections among GPC1 tumor-specific features is important because these tumors carry poor prognostic biomarkers." (PMID 32620753, 2020). "Here, we demonstrated concordant subtype-specific target pathway (BRCAness) activation with olaparib showing efficacy for GPC1 tumor-matched PDCs." (PMID 32620753, 2020). "The results indicated that the mCAR-T cells in both circulation and tumor retained GPC1-specific IFNγ producing activity for at least 15 days." (PMID 32228854, 2020). "Glypican-1 plays a critical role in tumour invasion, metastasis and progression and is overexpressed in various solid tumours, including PCa." (PMID 32382920, 2020). "The presence of GPC-1 in aggressive GBM is in line with the known role of GPC-1 in tumor angiogenesis and metastasis, making it an attractive target for molecular imaging and FGS of actively growing GBM regions." (PMID 32316186, 2020). "The ability of MIL-38-CD3 to activate T cells was assessed using in vitro co-culture assays with tumour cell lines of varying GPC-1 expression by measurement of CD69 and CD25 expression, before cytolytic activity was assessed in a similar co-culture." (PMID 33302918, 2020). "GPC1-specific murine mCAR-T cells specifically recognized mGPC1-positive tumor cells and eradicated solid tumors in vivo." (PMID 32228854, 2020). "In the xenograft and patient-derived tumour models, GPC-1-ADC significantly and potently inhibited tumour growth in a dose-dependent manner." (PMID 32152502, 2020). "After verifying an overall expression profile change mediated by GPC1, we proceeded to investigate how the proteoglycan would affect the tumor growth and its cells’ proliferation." (PMID 32180897, 2020). "GPC-1-ADC-mediated G2/M-phase cell cycle arrest was detected in the tumour tissues of GPC-1-ADC-treated mice relative to those of control-ADC-treated mice." (PMID 32152502, 2020). "In line with the role of GPC-1 in tumour progression, expression of GPC-1 increases with increasing Gleason Grade, suggesting its potential as a target for aggressive, difficult to treat lesions, including in mCRPC." (PMID 33302918, 2020). "By investigating GPC1+ exosome in the serum of patients with PC at pre- and post-surgery stages, this study demonstrated that the percentage of GPC1+ exosomes increased proportionally with tumor size and correlated with the tumor burden." (PMID 33297544, 2020). "To investigate the effect GPC-1 inhibition on gene expression in the TME we tested the effect of tumor condition media isolated from PC-3 cells on gene expression in human stromal cell lines such as mesenchymal stem cells (hMSCs) and fibroblasts (Hs27)." (PMID 31391540, 2019). "In contrast, the increase in tumor growth correlated to decreases in necrosis in tumors formed from GPC-1 shRNA." (PMID 31391540, 2019). "Secondly, ≥79% of the analysed clinical samples from urine of patients with localised PCa were positive for GPC-1+ putative tumour cells." (PMID 31905736, 2019). "We assessed the role of GPC-1 in cancer-stromal interactions by examining mRNA expression of a panel of genes believed to be important for recruiting stromal cells to the tumor niches." (PMID 31391540, 2019). "The data suggest that GPC-1 can possibly play a role as a tumor suppressor in DU-145 cells and the role of GPC-1 in mediating cell growth and migration is cell-type dependent." (PMID 31391540, 2019).